BPIFC (BPI fold containing family C)
Synonyms: BPIL2; dJ149A16.7
Tractability: Antibody: UniProt places it where antibodies can reach, with medium confidence; UniProt predicts a signal peptide or a membrane-spanning region; its Gene Ontology location is reachable by antibodies, with medium confidence.
Gene: Protein-coding gene on chromosome 22 (32,413,845 to 32,464,484, reverse strand). Ensembl gene ENSG00000184459.
Subcellular location: Secreted
Gene Ontology:
Molecular function: lipopolysaccharide binding; phospholipid binding; lipid binding
Cellular component: extracellular region
Genetic constraint (gnomAD): Loss-of-function variants: 49 observed, 49.62 expected, observed/expected ratio (o/e) 0.99, 90% interval 0.78 to 1.25. The upper end of that interval is the gene's LOEUF score, 1.25, which puts it in group 5 of 6, group 1 being the genes least tolerant of losing a copy. Missense variants: 503 observed, 544.73 expected, observed/expected ratio (o/e) 0.92, 90% interval 0.86 to 0.99. Synonymous variants: 213 observed, 206.43 expected, observed/expected ratio (o/e) 1.03, 90% interval 0.92 to 1.16.
Homologues: Orthologues: chimpanzee BPIFC (96% identical), macaque BPIFC (96% identical), dog BPIFC (86% identical), pig BPIFC (82% identical), guinea pig BPIFC (73% identical), mouse Bpifc (71% identical), rat Bpifc (70% identical). Paralogues in human: BPI (26% identical), PLTP (22% identical), LBP (21% identical), BPIFB3 (18% identical), BPIFB4 (18% identical), BPIFB2 (18% identical), CETP (17% identical), BPIFB6 (16% identical), BPIFB1 (14% identical), BPIFA2 (7% identical), BPIFA3 (7% identical), BPIFA1 (5% identical).
Diseases named in the same sentence as BPIFC in open-access papers:
BPIFC is named in the same sentence as 6 diseases in open-access papers, as found by Europe PMC text mining. Sharing a sentence is not in itself a finding about the gene and the disease. The quoted sentences say what the papers report.
hypertrophic cardiomyopathy (2 papers, 2024 to 2025). A condition in which the myocardium is hypertrophied without an obvious cause. "In addition, BPIFC was involved in the infiltration of naïve T CD4+ cells and T CD8+ cells in hypertrophic cardiomyopathy." (PMID 41153404, 2025).
cyst (1 paper, 2019). A sac-like closed membranous structure that may be empty or contain fluid or amorphous material. "Does it imply that the BPIFC protein, like the PLUNC family proteins, plays a role in the inflammation and then the formation of cyst, which remains to be validated by further studies." (PMID 31033252, 2019).
psoriasis (1 paper, 2019). An autoimmune condition characterized by red, well-delineated plaques with silvery scales that are usually on the extensor surfaces and scalp. "BPIFC protein is mainly expressed in human epidermis and highly expressed in the basal layer of the epidermis from inflammatory skin of patients with psoriasis." (PMID 31033252, 2019).
BPIFC also shares sentences with these, for which no sentence is quoted: myocardial hypertrophy (1 paper); trichilemmal cyst (1); tumor (1).